CD4 (CD4 molecule)
Diseases named in the same sentence as CD4 in open-access papers (continued):
Sharing a sentence is not in itself a finding about the gene and the disease.
infection (continued). "Following pathogen clearance in mice, antigen-specific CD4+ T cells can form a stable memory population that are reactivated during secondary infection." (PMID 33091023, 2020). "In three of six animals, highest levels of SIV DNA and/or SIV RNA as well as depletion of mucosal CD4+ T cells were already observed on day 7 after infection, designated as time point of ‘mucosal peak viral load’." (PMID 32616803, 2020). "Some ISGs are HIV restriction and virus inhibition factors that modulate productive infection in activated CD4+ T cells." (PMID 32109259, 2020). "Like Envs from other circulating HIV-1 strains, the wild type BF520 Env supported infection of cells engineered to express human CD4 and CCR5 (293Thu) but was severely restricted in its ability to infect cells expressing macaque receptors (293Trhm)." (PMID 32098152, 2020). "It is well known that IL-22 producing CD4+ T cells are essential for controlling Cr infection; however, the T cell-derived cytokines (IL17A, IFN-γ and TNF-α) contribute to intestinal tissue injury either directly or indirectly." (PMID 33076301, 2020). "At 2- and 6-weeks post-infection, the number of CD4+ and CD8+ T cells and their effector memory populations (CD62LloCD44hi) in the lungs were higher in Cse−/− mice than in WT." (PMID 33330130, 2020). "immunogenic proteins, it was reported that B. bovis small heat shock protein (Hsp20) is recognized by CD4+ T lymphocytes from cattle that recovered from infection and immune to challenge." (PMID 33233869, 2020). "Blockade of PD-1 and CTLA-4 and abrogation of IL-27R signaling thus raised the level of T-bet within the overall CD4+ T cell population, and this directly correlated with an increase in CD4+ T cell glycolytic metabolism during infection." (PMID 32817333, 2020). "It is rather a result of Treg specific defects during infection, because the effector CD4 cells in sham mice had comparable levels of cytokines in both FYcre and MFYcre mice." (PMID 33240286, 2020). "To ensure depletion of the CD4+ T cells, we measured CD4+ T cell percentages prior to infection in peripheral blood mononuclear cells (PBMCs) isolated from each group of mice and post-infection in the MLNs by flow cytometry." (PMID 32817694, 2020). "It was evident from the file reviews that changing treatment guidelines over the years has had an influence on ART initiation in this population, as they were more likely to be initiated in line with their CD4 cell count values at a later stage of infection." (PMID 32832111, 2020). "CD4+ T cells in Ehrlichia infection have shown to produce IFN-γ; in fact, IFN-γ KO mice were very susceptible to infection." (PMID 33233869, 2020). "Many studies have measured the expression of T-bet to reflect the level of CD4+ T cell differentiation and evaluate the host adaptive immune response after infection." (PMID 32431684, 2020). "Recent evidence provided some insight, indicating that TH1 and TH17-like CD4+ TRM cells can mobilize in response to infection." (PMID 32858901, 2020). "Using the particular strengths of human challenge infection, we have thus shown the breadth of CD4+ T cell targets in human RSV and demonstrate correlates of CD4+ T cell recruitment to the lung." (PMID 31815739, 2020). "Analysis of longitudinal data from an HIV-1B seroconverter cohort showed that higher levels of these CD4+ T-cell activation markers in early infection precede and independently predict subsequent emergence of X4-tropic viral strains." (PMID 32985522, 2020). "During infection, both CD4+ and CD8+ T cells became activated, as was shown by a downregulation of CD62L expression and an upregulation of CD44 expression, which corresponded with a Teff phenotype." (PMID 33664739, 2020). "In our rhesus macaque model, we found that a proportion of T cells, including Th1/Th2/Th17 cells, displayed a reduction during the middle and late stages of infection, while the CD4+FOXP3+T cell response was activated during this period." (PMID 33180882, 2020).
infection (continued). "It is also possible that our sampling of the first 3 years of infection was insufficient to observe alterations within Envs that significantly change cellular tropism for different CD4+ T cell subsets." (PMID 32762760, 2020). "As a major arm of the cellular immune response, CD4+ T cells are important in the control and clearance of infections." (PMID 33374787, 2020). "In conclusion, we show that the infection with SIV led to specific changes in DNA methylation in CD4 + T cells, in particular in the LN and already during primary infection." (PMID 33298174, 2020). "IFN-γ is the main pro-inflammatory cytokine secreted by CD4+ T cells, which helps in clearing Leishmania parasites during infection." (PMID 32103111, 2020). "We also observed virus-like particles in 1/10 fields at 6 h and 1/10 fields at 12 h after infection in CD4+ T cells." (PMID 32558639, 2020). "Our data suggests that multivariant infection plays a role in driving immune dysfunction in both the CD4+ T Cell and B cell compartments." (PMID 32886726, 2020). "A substantial decrease in the proportion of HIV-1-infected T cells during each additional year on ART was found for all lymph node-derived CD4+ T cell subsets from four participants treated during acute/early infection with paired PB and LN samples." (PMID 31723024, 2020). "CD4 T cells play important roles in the development of cellular and humoral immune responses following infection." (PMID 32733454, 2020). "To assess systemic cytokine levels in our C-IRIS model, we examined four major pro-inflammatory cytokines in sera from C-IRIS mice with three control conditions (naïve, CnH99-infection alone, and CD4+ T cell transfer alone)." (PMID 33133067, 2020). "Although the total number of GP66+ CD4+ T cells were similar in Ifnlr1−/- mice and littermate controls on day 7 post-infection, there were substantial differences in the cellular phenotype of the antigen-specific CD4+ T cell response." (PMID 32407154, 2020). "During murine infection with Mycobacterium tuberculosis, CD4+CD69+CXCR3+ TRM cells increase in the lung parenchyma." (PMID 32974217, 2020). "The CD4+ T lymphocyte subsets Th1 and Th17 have been shown to be protective in response to infection with C. neoformans, with Th1 be more widely studied in the literature." (PMID 33042164, 2020). "In our study we acknowledge that our CD4+ T cell subset tropism assay only detects productive infection through GFP expression." (PMID 32762760, 2020). "In the follicles, follicular dendritic cells can harbor infectious virus for extended periods of time promoting infection of newly recruited CD4 TFH cells." (PMID 32714317, 2020). "In the post-infection model, the inhibitory effect of Nullbasic was less robust, but suggested that Nullbasic provided CD4+ cells a survival benefit." (PMID 32276443, 2020). "After infection, the accumulation of activated lung CD4+ T cells is delayed by Mtb-mediated inhibition of early antigen presentation in the lymph nodes." (PMID 33105734, 2020). "Comparing the characteristics of WN virus-specific CD4 T cells in individuals with either neuroinvasive disease or asymptomatic infection, the same study found that individuals with neuroinvasive disease had higher numbers of virus-specific CD4 T cells." (PMID 32038660, 2020). "Activated CD4+ T cells from 3 different donors were infected at a low multiplicity of infection (MOI) to ensure that a majority of infected cells solely contained one virus per cell." (PMID 32807178, 2020). "The ability of CD4 T cells to produce cytokines deteriorated with prolonged infection, while dual blockade of PD-1 and LAG-3 with monoclonal antibodies restored the number of parasite specific CD4 T cells and their ability to secrete cytokines." (PMID 32793231, 2020). "Following PZQ therapy, the ratio of total CD4+:CD8+ T cells began to revert back toward the levels observed during the trickle infection." (PMID 32154190, 2020).
infection (continued). "In response to infection, naïve CD4+ T cells differentiate into distinct “helper” subsets with effector capacity, such as T helper 1 (TH1) and TH2 cells." (PMID 32858901, 2020). "The memory generation depends on CD4+ T-cell help, and infection of CD4+ T-cells results in impaired T-cell help." (PMID 33101401, 2020). "Cytokine-producing cell frequencies were not different between the 2 groups except CD4+ T cells collected on day 180 after infection increased IFN-γ expression compared with control CD4+ T cells." (PMID 32289501, 2020). "One study found around 5-20% of CD4+ T cells recognize Mtb-infected macrophages by 19- to 22-weeks post infection." (PMID 33552077, 2020). "This corresponded with increased parasite burden in mice infected with wildtype versus mif-/- L. major late in infection, suggesting a reduction in the formation of long-lived effector CD4 T cells in the presence of Leishmania MIF." (PMID 32244916, 2020). "This can lead to transmission and rapid spread of the infection to CD4+ T cells through cell-to-cell interactions." (PMID 32824563, 2020). "The fold change of FDC, pDC and CD3+CD4− T lymphocytes progressively increased over time of infection." (PMID 32351510, 2020). "We showed that upon infection, lymphocyte percentage declined, CD4 and CD8 T cells percentage within the lymphocyte population remained unchanged, and B cell percentage was relatively increased." (PMID 32975374, 2020). "Although HIV primarily infects CD4+ T cells, low-level infection of other cell types, including B cells, has been reported." (PMID 33318172, 2020). "In contrast to the control groups, the distribution of double-positive and triple-positive T cells in infection-induced CD4+ T-cell responses was higher in the lung cells from the group immunized with the Rv2299c-fused protein than with Ag85B-ESAT6." (PMID 33105734, 2020). "The initial descriptions of this showed convincing transfer of infection from the infected macrophages to the primary CD4+ T cells." (PMID 32354203, 2020). "While WT mice showed a significant increase in absolute numbers and frequency of GATA3+CD4+ T cells upon infection, Il17a-KO mice had a significantly lower frequency of GATA3+CD4+ T cells and failed to upregulate these cells on d7pi compared with WT controls." (PMID 32636457, 2020). "Further work is required to fully define the effects of the mTOR pathway on T-bet activity and on the function of effector CD4+ T cells during infection." (PMID 32817333, 2020). "Recent studies using an in vitro infection model of mDCs-CD4 T cells co-culture, had shown the contribution of PD1 engagement in the establishment of HIV latency." (PMID 32714317, 2020). "As T cells are crucial for control of virus replication, we examined in detail the CD8 and CD4 responses during H1N1pdm09 infection." (PMID 33603740, 2020). "Accordingly, high precursor frequencies of adoptively-transferred TCR-transgenic CD4+ T cells reduced the proliferation and differentiation of these cells upon infection, and thereby resulted in impaired memory T cell formation." (PMID 32106536, 2020). "If the smooth interaction factor z, the infection phase, has g=1..., G levels, the smooth curves of the response (CD4+ count) within each level (phase) are displayed separately." (PMID 32190387, 2020). "The frequencies of splenic CD4+ T cells expressing IFN-γ, IL-10 and TNF-α were found similar in vaccinated and control mice, whereas a reduction of CD4+IL-4+ cells frequency was observed upon infection in vaccinated mice." (PMID 32040500, 2020). "We sought to investigate the antigen (Ag)-specific CD4+ T cell response to Lm infection following primary and secondary (recall) infection to understand how CD4+ T cell memory evolves in the course of these responses." (PMID 32983171, 2020).
infection (continued). "When T and B cells were analyzed in the MLN of SD and taiep rats, we found that infection induced a reduction in the percentage of total T cells in both SD and taiep rats; and was observed equally for the CD4 T cell population." (PMID 32817660, 2020). "Neutrophils, Delta T cells, NK cells, and CD4+ T cells are activated to control the infection, leading to the formation of a granuloma." (PMID 33027958, 2020). "In this context, we show that CD4 T cell production of IFN-γ becomes critical to control of infection." (PMID 32669460, 2020). "Upon arrival at lymphoid tissues in mucosal transmission, HIV trans-infection to CD4+ T-follicular helper cells can occur." (PMID 32824563, 2020). "This CD4 T cell response is mainly mediated by Tbet-expressing, IFNγ-secreting Th1 cells, and it is necessary for resistance to the infection and final clearance of the bacteria in the tissues." (PMID 33042146, 2020). "Within 3–12 months of infection (early phase), the CD4+ cell count responded well to normal ALP and remained above average." (PMID 32190387, 2020). "Using a comparative infection model, we sequenced the splenic CD4+ T-cell receptor repertoires generated over the time-course of a Plasmodium chabaudi infection." (PMID 33329568, 2020). "The comparison of these two independents single-cell datasets drew an atlas of CD4+ T cell phenotypic features contrasting entry and productive infection." (PMID 32194526, 2020). "Longitudinal studies will be needed to understand the specific Th1/Th2 CD4+ Treg cell response during ANDV infection and their impact in immunopathogenesis." (PMID 32984065, 2020). "We observed that FTY720 was able to block infection in human CD4 T cells by hindering multiple steps in the life cycle of HIV." (PMID 32790802, 2020). "We performed splenic CD4+ T cell and B cell co-cultures to investigate the suppressive functions of B cells from mice at eight weeks post-infection." (PMID 32197642, 2020). "Several Salmonella proteins including flagellin and SseJ are responsible for inducing the Th1 and Th17 CD4+ T cell responses observed during infection, and B cell activation has been found to be required to activate Th1 and Th17 responses." (PMID 33604308, 2020). "While it is possible that the endogenous CD4+ T cells that accumulate in the lymph nodes and genital tract are specific to C. trachomatis, these T cells could also be specific to non-C. trachomatis antigen and accumulate in the tissues simply as a product of inflammation caused by infection." (PMID 32184237, 2020). "The effect HIV infection exerts on the GI mucosa is detrimental, with high levels of infection and destruction of CD4+ T cells and inflammation." (PMID 32876566, 2020). "CD4+ T cells (10x106) were adoptively transferred into γ-irradiated (sub-lethal dose of 800 rads/mice) Thy1.1+ congenic mice followed by infection with a low-dose aerosol challenge of M. tb strain H37Rv." (PMID 32956412, 2020). "One study in mice reported that SM infection impairs Mtb-specific TH1 CD4 T cell responses and increases arginase-1 expressing macrophages in type 2 granulomas." (PMID 32117277, 2020). "CD4 T-cell counts were significantly lower in PHI as compared to HIV-uninfected individuals (median 565 cells/μl at M2 after infection and 855 cells/μl, respectively, p < 0.001) and remained stable over the first year of infection." (PMID 33519823, 2020). "In blood, the frequency of activated CD4+ T cells increased between 7 and 10 days after infection, coinciding with viral clearance." (PMID 31815739, 2020). "In the early stages of the infection, the IL-17A is a crucial cytokine secreted by a wide range cell types such as Th17, B cells, innate lymphoid cells, CD4+, CD8+, gamma-delta T and invariant NKT10-13,32." (PMID 32193469, 2020). "Infection of primary CD4+ T-cells with V1/HA-Vpr and V1/δ-Vpr revealed that the presence of Vpr resulted in ~2 fold higher levels of GFP expression than did in its absence." (PMID 32538781, 2020).
infection (continued). "Further characterization has indicated that productive infection, particularly proviral DNA integration, is required for cGAS-dependent DNA sensing in activated CD4+ T cells." (PMID 31968566, 2020). "Factors like patient’s occupational exposure, medical history, a cluster of differentiation-4 +T- cells (CD4 + T-cells) count, viral load levels, and endemic infections are of significant importance and should be considered while managing these patients." (PMID 33209528, 2020). "Th17 cells are a specialized subset of CD4 + T cells that are essential in driving inflammation and infection through a signature cytokine IL‐17." (PMID 32820615, 2020). "In the adjuvant and blank control groups, a small increase in CD3+CD4+ T cell population was observed after infection compared to the level detected before infection, whereas the percentage of CD3+CD8+ T cells significantly increased after the challenge." (PMID 32334611, 2020). "Subsequently, infection of CD4+ T cells takes place through interaction between viral gp120 and T cell co-receptors such as CCR5 or CXCR4." (PMID 32876566, 2020). "Epitopes can also be exposed on infected cells by triggering the CD4 remaining at the cell surface post-infection or with a mixture of small CD4-mimetic compounds and coreceptor-specific antibodies." (PMID 32605979, 2020). "While neutrophils are readily detected in infected airways CD8+ and CD4+ T cells needed to clear infection are often only detected at low levels." (PMID 32509597, 2020). "In the survival analysis, triple infection showed more faster CD4+ T-cell decline than double and single infection (P < 0.05)." (PMID 32038599, 2020). "Upon challenge infection with P. berghei, vaccinated mice showed a significant increase in CD4+ and CD8+ effector memory T cell and memory B cell populations." (PMID 32751598, 2020). "We show that in this immunodeficient background on a BALB/c background, CD4 T cells become important effector cells and are able to protect Batf3−/− mice from infection with the avirulent strain RHΔku80Δrop5." (PMID 32669460, 2020). "CD4+ T cells, also called helper T (Th) cells, contribute to immune responses against infections by providing help to B cells and CD8+ T cells." (PMID 33291260, 2020). "In mouse models of infection, expression of Ly6C has been used to identify highly differentiated CD4+ T effector cells." (PMID 33193363, 2020). "Our data suggest that more differentiated memory CD4+ T cell subsets (TM and EM) are preferentially targeted for infection by C-HIV Envs in vitro, and that tropism remained consistent during progression from acute to chronic disease." (PMID 32762760, 2020). "(E) t-SNE plots of uninfected and PRE cells demonstrate that the dominant population of T cells targeted for infection in both blood and endometrium are memory CD4+ T (Tm) cells." (PMID 32452381, 2020). "In the present study, we examined the effect of bNAbs on HIV-1 capture and replication using human PBMCs and purified CD4+ T cells as target cells to understand the early steps of infection." (PMID 33371189, 2020). "We performed KSHV infections in which total lymphocytes, CD4-depleted total lymphocytes or CD8-depleted total lymphocytes were added back following infection of sorted naïve B cells." (PMID 33075105, 2020). "CD4+BrdU+ effector T cells from AK085865−/− mice 7 days post‐infection were significantly increased compared to WT mice." (PMID 32220054, 2020). "Detection of intracellular expression of IFN-γ has been previously reported in CD8+ T cells in a viral (although limited amounts) infection or in CD4+ and CD8+ T cells in Mycobacterium tuberculosis infection in the lung of mice without BFA treatment." (PMID 32013893, 2020). "After Con-A stimulation, the fold change in CD4:CD8b ratio (vs. unstimulated PBMCs) was markedly increased in one koala with endogenous infection only (H6; KoRV-A positive) and one koala positive for both exogenous subtypes (H7; KoRV-A, -B, and -C positive)." (PMID 33316950, 2020).